NKX2-5 (NK2 homeobox 5)
Description:
Transcription factor required for the development of the heart and the spleen. During heart development, acts as a transcriptional activator of NPPA/ANF in cooperation with GATA4 (By similarity). May cooperate with TBX2 to negatively modulate expression of NPPA/ANF in the atrioventricular canal (By similarity). Binds to the core DNA motif of NPPA promoter. Together with PBX1, required for spleen development through a mechanism that involves CDKN2B repression. Positively regulates transcription of genes such as COL3A1 and MMP2, resulting in increased pulmonary endothelial fibrosis in response to hypoxia.
Synonyms: CSX; NKX2.5; NKX2E; CSX1; NKX4-1; CHNG5; HLHS2; VSD3
Tractability: No criterion of Open Targets' tractability assessment is met for any kind of drug.
Gene: Protein-coding gene on chromosome 5 (173,232,109 to 173,235,311, reverse strand). Ensembl gene ENSG00000183072.
Subcellular location: Nucleus
Subcellular location (Human Protein Atlas): Nucleoplasm; Cytosol
Pathways (Reactome):
Developmental Biology: Cardiogenesis
Gene expression (Transcription): YAP1- and WWTR1 (TAZ)-stimulated gene expression
Muscle contraction: Physiological factors
Gene Ontology:
Molecular function: chromatin binding; DNA binding; DNA-binding transcription activator activity; DNA-binding transcription activator activity, RNA polymerase II-specific; DNA-binding transcription factor activity; protein binding; RNA polymerase II cis-regulatory region sequence-specific DNA binding; RNA polymerase II-specific DNA-binding transcription factor binding; sequence-specific DNA binding; sequence-specific double-stranded DNA binding; transcription cis-regulatory region binding; DNA-binding transcription factor activity, RNA polymerase II-specific; protein homodimerization activity
Biological process: adult heart development; atrial septum morphogenesis; cardiac conduction system development; cardiac muscle tissue morphogenesis; negative regulation of cardiac muscle cell apoptotic process; negative regulation of myotube differentiation; negative regulation of transcription by RNA polymerase II; outflow tract septum morphogenesis; positive regulation of DNA-templated transcription; positive regulation of neuron differentiation; positive regulation of transcription by RNA polymerase II; regulation of DNA-templated transcription; right ventricular cardiac muscle tissue morphogenesis; septum secundum development; spleen development; thyroid gland development; ventricular septum morphogenesis; aortic valve morphogenesis; atrial cardiac muscle cell development; atrial cardiac muscle tissue development; atrioventricular node development; bundle of His development; cardiac muscle cell development; cell differentiation; embryonic heart tube development; and 20 more
Cellular component: Nkx-2.5 complex; nucleoplasm; nucleus; protein-containing complex; protein-DNA complex; RNA polymerase II transcription regulator complex; chromatin; transcription regulator complex; cytoplasm
Genetic constraint (gnomAD): Loss-of-function variants: 3 observed, 24.15 expected, observed/expected ratio (o/e) 0.12, 90% interval 0.056 to 0.32. The upper end of that interval is the gene's LOEUF score, 0.32, which puts it in group 1 of 6, group 1 being the genes least tolerant of losing a copy. Missense variants: 429 observed, 449.4 expected, observed/expected ratio (o/e) 0.95, 90% interval 0.88 to 1.03. Synonymous variants: 215 observed, 215.99 expected, observed/expected ratio (o/e) 1, 90% interval 0.89 to 1.12.
Gene-disease validity (ClinGen):
ClinGen rates the evidence that NKX2-5 causes each of these diseases.
NKX2.5-related congenital, conduction and myopathic heart disease (autosomal dominant): Definitive. A heart disease that includes congenital heart defects, abnormal cardiac conduction or myopathy.
Homologues: Orthologues: chimpanzee NKX2-5 (99% identical), macaque NKX2-5 (98% identical), pig NKX2-5 (95% identical), rabbit NKX2-5 (95% identical), dog NKX2-5 (94% identical), rat Nkx2-5 (89% identical), mouse Nkx2-5 (88% identical), guinea pig NKX2-5 (85% identical), tropical clawed frog nkx2-5 (60% identical), zebrafish nkx2.5 (53% identical), Drosophila melanogaster scro (29% identical), Caenorhabditis elegans ceh-24 (27% identical), and 5 more. Paralogues in human: NKX2-3 (49% identical), NKX2-6 (40% identical), NKX2-4 (32% identical), NKX2-1 (31% identical), NKX2-2 (27% identical), NKX3-2 (25% identical), NKX2-8 (25% identical), NKX3-1 (23% identical), NKX1-1 (18% identical), NKX1-2 (18% identical), NKX6-1 (14% identical), NKX6-2 (14% identical), and 1 more.
Diseases named in the same sentence as NKX2-5 in open-access papers:
NKX2-5 is named in the same sentence as 148 diseases in open-access papers, as found by Europe PMC text mining. Sharing a sentence is not in itself a finding about the gene and the disease. The quoted sentences say what the papers report.
congenital heart disease (63 papers, 2009 to 2025). A heart disease that is present at birth. "It is highly likely that this variant leads to a complete loss of NKX2-5 function, indicating haploinsufficiency as the underlying pathophysiology in this nonsyndromic congenital heart disease family." (PMID 40704064, 2025). "Congenital heart disease (CHD) represents a prevalent group of structural cardiac anomalies often associated with alterations in key transcription factors including NKX2-5, TBX5, and, particularly, GATA4." (PMID 40430071, 2025). "Here we reported a NKX2-5 nonsense variant in a Chinese family with nonsyndromic congenital heart disease." (PMID 40704064, 2025). "NK2 HOMEOBOX 5(OMIM: 600584, NKX2-5), a pivotal cardiac regulatory transcription factor, represents the initial identified genetic etiology underlying congenital heart diseases (CHDs)." (PMID 40704064, 2025). "Specifically, we targeted the downstream core promoter element (DPE) of the endogenous tin gene, encoding the Tinman transcription factor, a homologue of human NKX2-5 associated with congenital heart diseases." (PMID 38958007, 2024). "Mutations in this gene and its counterpart, NKX2-5, have been linked to various congenital heart defects." (PMID 37626805, 2023). "The homeodomain transcription factor, NKX2-5, is one of the most commonly mutated genes associated with human congenital heart disease (CHD) and is a master regulator of cardiac development." (PMID 35624100, 2022). "We applied intermittent mild hyperoxia (40% O2, 10 h per day) to wild-type pregnant mice with the expectation of having fetuses with genetic congenital heart disease induced by an Nkx2-5 mutation from gestational day 8.5 to birth." (PMID 33758249, 2021). "The role of NKX2-5 polymorphism (rs2277923) in the pathogenesis of congenital heart disease was checked by calculating the pooled odds ratio (ORs) and 95% confidence interval (CI)." (PMID 34417931, 2021). "NK2 homeobox 5 (Nkx2.5), a homeobox-containing transcription factor, is associated with a spectrum of congenital heart diseases." (PMID 33869046, 2021). "Altered heterozygous CSX/NKX2‐5 mutations were established in congenital heart defects patients in an autosomal dominant fashion." (PMID 30834692, 2019). "Heterozygous mutations in transcription factor gene NKX2‐5 are connected to either isolated or combined congenital heart disease (CHD), primarily secundum atrial septal defect‐II (ASD‐II), ventricular septal defect (VSD) or tetralogy of Fallot (TOF)." (PMID 30834692, 2019). "Because mutations in NKX2-5 are associated with a myriad of congenital heart diseases (CHD) in humans, this transcription factor has received much attention for its role in cardiac morphogenesis." (PMID 29979676, 2018). "In humans, NKX2-5 is also one of the most commonly mutated single genes in congenital heart disease (CHD), with heterozygous mutations causative for a spectrum of CHD phenotypes, most prominently atrial septal defects and progressive conduction block." (PMID 27683156, 2016). "We also found that the interaction of RXRα with NKX2-5 mutations found in congenital heart disease (Q187H, R189G and R190H) was altered." (PMID 27683156, 2016). "In human congenital heart disease, there are known mutations in cardiac-specific transcription factor genes that impact protein function and the NK2 transcription factor related, locus 5 gene (NKX2-5) provides a good example of this." (PMID 28536625, 2016). "This review summarizes the genetic etiology of congenital heart defects and emphasizes the need for NKX2-5 mutation screening." (PMID 26805889, 2016). "In humans, mutations in the NKX2-5 gene cause congenital heart disease; haploinsufficiency results in a spectrum of congenital heart disease of varying phenotypic penetrance, which is mirrored in mouse models." (PMID 26411676, 2015).
congenital heart disease (continued). "In humans, NKX2-5 is one of the most commonly mutated single genes in congenital heart disease (CHD), with dominant alleles causing atrial septal defect and atrioventricular conduction block most commonly, and a host of more severe defects at lower penetrance." (PMID 26146939, 2015). "Numerous mutations in NKX2-5 have been reported in individuals with congenital heart disease (CHD), but recently a select few have been associated with thyroid dysgenesis, among which the p.A119S variation." (PMID 23285148, 2012). "NKX2-5 mutations have been found in a subset of patients with congenital heart disease (CHD), mostly septal defects." (PMID 23285148, 2012). "Although the association between NKX2-5 gene variants and various congenital heart diseases is well-established, the genotype-phenotype correlation of these variants in heart diseases remains unclear." (PMID 40704064, 2025). "The present study identified a heterozygous nonsense variant of the NKX2-5 gene in a family with nonsyndromic congenital heart disease, suggesting that this variant may be the underlying cause of the disease within this particular family." (PMID 40704064, 2025). "We used the Drosophila system to analyze a variant of unknown significance in the human congenital heart disease gene NKX2.5 (also known as NKX2-5)." (PMID 37691628, 2023). "Meanwhile, normal Gata4 and Nkx2-5 activities might drive normal cardiac development and the mutation events on Gata4 and Nkx2-5 were considered as the causes of the occurrence and development of congenital heart disease." (PMID 36318264, 2023). "In humans, mutations in Csx/NKX2-5 are strongly associated with congenital heart diseases." (PMID 35185581, 2022). "Furthermore, we found that interactions between RXRα and a subset of NKX2-5 mutations causative for congenital heart disease (Q187H, R189G and R190H) were altered, linking TF–TF interaction networks to heart disease." (PMID 27683156, 2016). "NKX2-5 mutations are associated with different forms of congenital heart disease." (PMID 25742962, 2015). "Two mutant versions of NKX2-5 were also investigated: one, called NKX2-5Y191C, harbors a mutation located within the homeodomain – the region of NKX2-5 that binds to DNA – that has been linked to congenital heart disease; and another that completely lacks the homeodomain." (PMID 26305497, 2015). "Our study reveals binding and activities of NKX2-5 mutations on WT target and off-targets, guided by interactions with their normal cardiac and general cofactors, and suggest a novel type of gain-of-function in congenital heart disease." (PMID 26146939, 2015). "Thus, it is conceivable that, in addition to mutations in the protein coding region of NKX2-5, homozygous or heterozygous mutations in downstream core promoter motifs of NKX2-5 could likewise be responsible for congenital heart defects." (PMID 38958007, 2024). "The association with the genes NKX2-5, NOTCH1, GATA4, GATA6 and HAND1 links trabeculation to congenital heart disease (CHD)." (PMID 39567769, 2024). "Two sSNVs in NKX2-5, identified in patients with congenital heart disease, decreased the mRNA's transactivation potential." (PMID 33822938, 2021). "NKX2‐5 and GATA4 were the first congenital heart disease–causing genes identified by linkage analysis." (PMID 30834692, 2019). "In particular, transcription factors NKX2–5, GATA4, and TBX5 have been identified as playing central roles in the development of the heart, and mutations in these genes are involved in congenital heart disease (McCulley and Black 2012, p." (PMID 32009681, 2017). "Aberrations in the NKX2-5 transcription factor have been reported in various types of congenital heart defects and are spread across various domains on the gene." (PMID 26805889, 2016). "The research performed to establish the etiology of congenital heart defects implicates aberrations in genes, with the NKX2-5 gene being the prime suspect." (PMID 26805889, 2016).
congenital heart disease (continued). "Germline mutations in cardiac-specific transcription factor genes have been associated with congenital heart disease (CHD) and the homeodomain transcription factor NKX2-5 is an important member of this group." (PMID 24376681, 2013). "Although mutations of NKX2-5, HAND1 and TBX20 have been found in patients with TOF, they are present only in a small percentage of patients with congenital heart disease." (PMID 22672592, 2012). "First-generation (F1) hybrids of the inbred strains C57BL/6N and FVB/N or A/J were found to have a lower incidence of congenital heart defects than Nkx2-5+/− mice in the C57BL/6N background or the second-generation (F2) offspring of backcrosses to the parental strains or intercrosses (F1×F1)." (PMID 34573350, 2021). "Although some recent studies have studied the role of polymorphisms in the NKX2-5 gene in congenital heart diseases (CHDs), the results were not consistent and remained uncertain." (PMID 34417931, 2021). "Moreover, Nkx2-5 gene dosage is clearly important in heart development, because haploinsufficiency for NKX2-5 gives rise to congenital heart disease in man." (PMID 27606604, 2016). "Mice lacking NKX2-5 have abnormal hearts and many humans who are born with congenital heart disease carry mutations in the gene that encodes this protein." (PMID 26146939, 2015). "On the other hand, it seems that the role of genes, such as GATA4, TBX5, NKX2-5, HOMEZ, PLAGL1, and CITED2, in heart development is significant, as numerous studies on knockout mice report that mutations in these genes are frequently associated with VSD or other congenital heart anomalies." (PMID 39466144, 2025). "Though alterations in NKX2‐5 are linked to an extensive variety of CHDs and thyroid dysgenesis, NKX2‐5 codes for a homeodomain–containing transcription factor with an important role in heart development, and mutations affecting this gene in individuals with congenital heart disease were reported." (PMID 30834692, 2019). "In addition to two polymorphisms of NKX2‐5 (rs2277923, rs28936670) variant in the cardiac septal defect, two variants in GATA4 (rs368418329, rs56166237) and one variant in TBX5 (rs6489957) seem to have a role in the pathogenesis of congenital heart disease." (PMID 30834692, 2019). "Cardiogenic transcription factors, such as NKX2-5, TBX5 and GATA4, play critical roles in ensuring that the embryonic heart forms properly, and dominant mutations in the genes that encode these transcription factors have been implicated in the development of congenital heart defects." (PMID 26305497, 2015). "NKX2-5, CAV1 and ATP2A2 in the integrin signaling and cardiac hypertrophy signaling (enhanced) pathways were also involved in the toxicity pathways such as failure of heart, congenital heart disease, congestive heart failure, dilation of heart chamber and dilation of left ventricle." (PMID 31948008, 2020). "Interestingly, several genes including NKX2-5, ATP2A2 and CAV1 involved in these pathways were also found in toxicity pathways such as failure of heart, congenital heart disease, congestive heart failure, dilation of heart chamber and dilation of left ventricle." (PMID 31948008, 2020).
atrial septal defect (45 papers, 2008 to 2025). Interauricular communication is a congenital malformation characterized by a communication between the atrial chambers of the heart. "NKX2-5 is a key regulator of myocardial differentiation and septation, with variants showing association with atrial septal defect, tetralogy of Fallot, atrioventricular nodal reentrant tachycardia and AF." (PMID 41172738, 2025). "Previous studies have reported a genetic variant of NKX2-5 linked to the development of atrial septal defect." (PMID 35459168, 2022). "Here, we screened the NKX2-5 variants in patients with atrial septal defect (ASD) in the Indonesian population." (PMID 35459168, 2022). "Human mutations of NKX2-5 cause a variety of heart malformations including: AV conduction abnormalities, AV block, atrial septal defect, VSD and Tetralogy of Fallot." (PMID 30840660, 2019). "The mutations in various genes have been associated with atrial septal defects, for instance, mutations in NKX2–5, GATA4, TBX5, and MYH6." (PMID 29969989, 2018). "The intermittent atrial communication defect is a patent foramen ovale, which was also found in mice heterozygous for Nkx2-5, a gene also implicated in human atrial septal defects." (PMID 22589735, 2012). "Cao Y‘s study in 2016 suggested that a variation in the single nucleotide site of NKX2-5 may be linked to the occurrence of Atrial Septal Defect (ASD)." (PMID 38808331, 2024). "NKX2-5 variant in atrial septal defect patients has been reported." (PMID 35459168, 2022). "Here, we screened the NKX2-5 variants in patients with atrial septal defect in Indonesia." (PMID 35459168, 2022). "The most prevalent cardiac anomaly demonstrated in human patients with missense mutations in the NKX2-5 homeodomain is atrial septal defects, characterized by persistent communications between the left and right atria, permitting postnatal shunting from left-to-right." (PMID 30151366, 2018). "Mice with atrial-specificdeficiency of Nkx2-5 frequently exhibit major atrial abnormalities, suchas atrial septal defects (ASDs), supraventricular bradycardia, and atrialconduction block." (PMID 40351691, 2025). "Genetic mutations in cardiac transcription factor genes such as NKX2-5, GATA4, TBX5 and MYH6, located in chromosome 14q12, have been associated with atrial septal defects." (PMID 40843896, 2025). "The genes in this cluster included Nkx2-5, Myh6, Tbx5, and ten others, which were preferentially related to the CHDs like atrial septal defect (ASD) and ventricular septal defect (VSD)." (PMID 36575170, 2022). "Other potentially involved genes (GATA Binding Protein 4, GATA4; T-Box Transcription Factor 20, TBX20; NK2 Homeobox 5, NKX2-5; Zic Family Member 3, ZIC3) were initially recognized as pathogenic for Atrial Septal Defects (ASD)." (PMID 34946902, 2021). "As expected, Nkx2-5+/− mice have an increased incidence of atrial septal defects (ASDs), membranous VSDs and muscular VSDs compared to the Nkx2-5WT." (PMID 28406175, 2017). "The majority of cases are sporadic, but some are inherited and associated with mutations in specific genes such as NKX2-5 (also associated with atrioventricular conduction defects), GATA4, TBX5 (associated with Holt–Oram syndrome) and MYH6 (implied in septal defects)." (PMID 40843896, 2025). "Likewise, the NKX2-5 mutation, which causes isolated CHD, is most commonly associated with atrial septal defects, although severe defects such as tetralogy of Fallot and double outlet right ventricle were reported." (PMID 34573350, 2021). "We describe a family with a novel missense mutation in the NKX2-5 gene (p.Gln181Pro) with numerous antecedents with atrial septal defect (ASD), left ventricular non-compaction (LVNC), conduction disease, and sudden cardiac death (SCD)." (PMID 34277740, 2021). "As a negative control we also used the p.N188K NKX2-5 mutant, reported as causative in a family with five affected presenting with atrial septal defects, Ebsteins anomaly and abnormal AV conduction." (PMID 23285148, 2012).